TMEM163 (transmembrane protein 163)
Description:
Zinc ion transporter that mediates zinc efflux and plays a crucial role in intracellular zinc homeostasis. Binds the divalent cations Zn(2+), Ni(2+), and to a minor extent Cu(2+) (By similarity). Is a functional modulator of P2X purinoceptors, including P2RX1, P2RX3, P2RX4 and P2RX7. Plays a role in central nervous system development and is required for myelination, and survival and proliferation of oligodendrocytes.
Synonyms: DKFZP566N034; SV31; SLC30A11; DC29; HLD25
Tractability: Antibody: UniProt places it where antibodies can reach, with high confidence; UniProt predicts a signal peptide or a membrane-spanning region; its Gene Ontology location is reachable by antibodies, with medium confidence. PROTAC: ubiquitination databases record sites on it; its protein half-life has been measured.
Gene: Protein-coding gene on chromosome 2 (134,455,759 to 134,719,100, reverse strand). Ensembl gene ENSG00000152128.
Subcellular location: Cytoplasmic vesicle, secretory vesicle, synaptic vesicle membrane; Early endosome membrane; Late endosome membrane; Lysosome membrane; Cell membrane
Gene Ontology:
Molecular function: protein binding; zinc ion binding
Biological process: intracellular zinc ion homeostasis; myelination; zinc export across plasma membrane; zinc ion import into synaptic vesicle
Cellular component: intracellular vesicle; late endosome; late endosome membrane; lysosomal membrane; lysosome; plasma membrane; early endosome membrane; synaptic vesicle membrane; cytoplasmic vesicle; endomembrane system; membrane
Genetic constraint (gnomAD): Loss-of-function variants: 15 observed, 22.55 expected, observed/expected ratio (o/e) 0.67, 90% interval 0.44 to 1.02. The upper end of that interval is the gene's LOEUF score, 1.02, which puts it in group 4 of 6, group 1 being the genes least tolerant of losing a copy. Missense variants: 289 observed, 341.6 expected, observed/expected ratio (o/e) 0.85, 90% interval 0.77 to 0.93. Synonymous variants: 154 observed, 144.13 expected, observed/expected ratio (o/e) 1.07, 90% interval 0.94 to 1.22.
Gene-disease validity (ClinGen):
ClinGen rates the evidence that TMEM163 causes each of these diseases.
leukodystrophy, hypomyelinating, 25 (autosomal dominant): Moderate.
Homologues: Orthologues: chimpanzee TMEM163 (100% identical), macaque TMEM163 (98% identical), pig TMEM163 (94% identical), rabbit TMEM163 (93% identical), dog TMEM163 (92% identical), mouse Tmem163 (91% identical), rat Tmem163 (83% identical), guinea pig TMEM163 (77% identical), tropical clawed frog tmem163 (69% identical), zebrafish tmem163b (65% identical), zebrafish tmem163a (62% identical).
Diseases named in the same sentence as TMEM163 in open-access papers:
TMEM163 is named in the same sentence as 28 diseases in open-access papers, as found by Europe PMC text mining. Sharing a sentence is not in itself a finding about the gene and the disease. The quoted sentences say what the papers report.
type 2 diabetes (4 papers, 2018 to 2022). "In addition, TMEM163 was also shown to be highly expressed in insulin secretory vesicles in human pancreas, and has been identified as a risk factor in type 2 diabetes." (PMID 35901096, 2022). "Previous studies suggest the involvement of TMEM163 in insulin secretion and type 2 diabetes pathogenesis." (PMID 35207731, 2022). "Moreover, TMEM163 mRNA expression in human pancreatic tissue from patients with type 2 diabetes was significantly increased." (PMID 35207731, 2022). "Notably, several age-downregulated genes, such as Plxdc2, Igf1, Igf2bp3, and Igf1r, and upregulated genes, such as Adam19 and Tmem163, have been linked to IGF signaling or type 2 diabetes." (PMID 30180872, 2018).
diabetes (3 papers, 2021 to 2022). "Single nucleotide polymorphisms (SNPs) in TMEM163 have been reported to be associated with an increased risk of Parkinson’s disease and diabetes." (PMID 35455965, 2022). "We also examine recent reports that implicate TMEM163 directly or indirectly in various human diseases such as Parkinson’s disease, Mucolipidosis type IV and diabetes." (PMID 33670071, 2021). "Recent Genome-Wide Association Study (GWAS) reports have implicated TMEM163 in Parkinson’s disease and diabetes; however, no mutations within TMEM163 have been confirmed in these mono-genetic disorders." (PMID 35455965, 2022).
leukodystrophy (3 papers, 2022 to 2023). Leukodystrophies are a group of rare, progressive, metabolic, genetic diseases that affect the brain, spinal cord and often the peripheral nerves. "Recently, two patients with hypomyelinating leukodystrophy were found to carry two unique de novo variants of TMEM163." (PMID 36003149, 2022). "Our findings suggest an unappreciated role for TMEM163 protein in myelin development and add TMEM163 to a growing list of genes associated with hypomyelination leukodystrophy." (PMID 35455965, 2022). "We show for the first time that TMEM163 plays a role in oligodendrocyte development and function, as well as being a novel gene associated with hypomyelination leukodystrophy." (PMID 35455965, 2022). "Here, we first propose TMEM163 as a disease-causing gene of a neurologic disease, hypomyelination leukodystrophy." (PMID 35455965, 2022). "Our findings reveal a novel role of zinc homeostasis in oligodendrocyte development and myelin production and show that variations in TMEM163 induce hypomyelination leukodystrophy." (PMID 36950148, 2023).
mucolipidosis type IV (2 papers, 2021 to 2022). A lysosomal disease characterized by psychomotor delay, progressive visual impairment, and achlorhydria. "Additionally, the expression of TMEM163 was found reduced in patients with Mucolipidosis type IV or HPS." (PMID 35455965, 2022).
autoimmune disease (1 paper, 2022). A disorder resulting from loss of function or tissue destruction of an organ or multiple organs, arising from humoral or cellular immune responses of the individual to their own tissue constituents. "Genetic variation affecting TMEM163 expression has not previously been implicated in the pathogenesis of autoimmune disease." (PMID 35835762, 2022). "We expand on these findings, leveraging our NK eQTL data to perform TWAS in five autoimmune diseases, defining novel roles for NK cell expression of CD226 and TMEM163 in systemic lupus erythematosus and primary biliary cirrhosis." (PMID 35835762, 2022).
hepatocellular carcinoma (1 paper, 2024). A malignant tumor that arises from hepatocytes. "Namely, TMEM163 implied in NK cell degranulation was down-regulated whereas SIGLEC10, which is thought to decrease NK cell cytotoxicity in hepatocellular carcinoma, was up-regulated." (PMID 39867888, 2024).
Hermansky-Pudlak syndrome (1 paper, 2026). Hermansky-Pudlak syndrome (HSP) is a multi-system disorder characterized by oculocutaneous albinism, bleeding diathesis and, in some cases, neutropenia, pulmonary fibrosis, or granulomatous colitis. "Transmembrane protein 163 (TMEM163), a zinc transporter, is drastically reduced in platelets of AP-3-, BLOC-1-, and BLOC-2-deficient Hermansky-Pudlak syndrome mice and patients, but the mechanistic basis is unclear." (PMID 41985787, 2026).
itch (1 paper, 2024). "To test the role of Tmem163 in aging-related Zn2+ accumulation in the spinal dorsal horn and aging-related itch, we generated Tmem163 conditional knockout (cKO) mice in which Tmem163 was selectively deleted in VGluT1+ DRG neurons." (PMID 39602426, 2024). "To unravel the specific involvement of vesicular Zn2+ stored in the central terminals of TMEM163+ primary afferents in mediating aging-related itch, we investigated the postsynaptic neurons of these primary afferents within the spinal cord." (PMID 39602426, 2024). "Collectively, these findings provide compelling evidence that the Zn2+ transporter TMEM163 mediates the accumulation of Zn2+ in large-sized DRG neurons and the deep laminae of the spinal dorsal horn, thereby playing a vital role in the pathogenesis of aging-related itch." (PMID 39602426, 2024).
lymph node metastasis (1 paper, 2025). "Transcriptomic profiling revealed a molecular signature (ALDH1A3, CTXN1, MGAT3, and TMEM163) of occult lateral lymph node metastasis, exhibiting strong robustness (AUC = 0.857)." (PMID 40977710, 2025).
lymphoma (1 paper, 2022). A malignant (clonal) proliferation of B- lymphocytes or T- lymphocytes which involves the lymph nodes, bone marrow and/or extranodal sites. "The role of M0, M2 macrophages in tumor immune microenvironment is consistent with the favorable genes of CHIT1, SIGLEC15, PLA2G2D and TMEM163 for the prognosis of lymphoma patients." (PMID 36249005, 2022). "We reported that down-regulation of CHIT1, SIGLEC15, PLA2G2D and TMEM163 was associated with poor prognosis in immunocompetent NHL, and expression levels of four genes were lower in lymphoma than in normal tissues." (PMID 36249005, 2022). "Four differential genes between EBV+ and EBV- lymphoma patients were screened out with the significance of the survival and prognosis of lymphoma, including CHIT1, SIGLEC15, PLA2G2D and TMEM163." (PMID 36249005, 2022). "CHIT1 and TMEM163 have been identified using RT-qPCR and are able to function as potential novel therapeutic targets for EBV+ lymphoma patients." (PMID 36249005, 2022). "Our data suggest that differences in expression levels of CHIT1 and TMEM163 and macrophage infiltration levels may be important drivers of poor prognosis of EBV+ lymphoma patients." (PMID 36249005, 2022).
neuroblastoma (1 paper, 2024). Neuroblastoma (NB) is the most common solid, extracranial childhood tumor. "Then, we induced overexpression of TMEM163-EGFP and VGluT1-mCherry in the ND7/23 cell line, a hybridized cell line consisting of mouse neuroblastoma and rat DRG neurons." (PMID 39602426, 2024).
primary biliary cirrhosis (1 paper, 2022). "We also identified NK cell expression of TMEM163 as a determinant of primary biliary cirrhosis." (PMID 35835762, 2022).
xerosis (1 paper, 2024). "Notably, TMEM163 expression significantly increases with aging and in xerosis conditions, resulting in enhanced Zn2+ loading into presynaptic vesicles." (PMID 39602426, 2024).
tumor (5 papers, 2022 to 2026). "TMEM163 acts as a tumor-suppressive gene in LUAD; higher expression correlates with reduced mortality risk and is part of a four-gene signature (HLF–CHRDL1–SELENBP1–TMEM163) that robustly predicts better OS across four independent LUAD cohorts." (PMID 41596760, 2026). "The overexpression of TMEM163, induced by the oncogene Src, has been demonstrated to facilitate the migration of transformed tumor cells." (PMID 40977710, 2025).
cancer (2 papers, 2017 to 2022). A tumor composed of atypical neoplastic, often pleomorphic cells that invade other tissues. "Despite there being no significant change in TMEM163 in the normal and cancer tissues, the overall expression levels of TMEM163 were higher in normal tissues than in adjacent tissues." (PMID 35205284, 2022). "Additionally, some of the remaining genes in the FLC mRNA signature including, TMEM163, TNRC6C, and C10orf128 have yet to be extensively characterized in cancer." (PMID 28304380, 2017).
TMEM163 also shares sentences with these, for which no sentence is quoted: Parkinson disease (3 papers); autism spectrum disorder (1); breast carcinoma (1); breast neoplasm (1); Crohn disease (1); genetic disorders (1); gestational diabetes (1); Hydrocephalus (1); Insulin resistance (1); neurologic disease (1); Obesity (1); systemic lupus erythematosus (1); ulcerative colitis (1).